RXFP3 (relaxin family peptide receptor 3)
Description:
Receptor for RNL3/relaxin-3. Binding of the ligand inhibit cAMP accumulation.
Synonyms: GPCR135; RLN3R1; SALPR; RXFPR3
Tractability: Small molecule: a high-quality ligand is known; it belongs to a druggable protein family. Antibody: its Gene Ontology location is reachable by antibodies, with high confidence; UniProt places it where antibodies can reach, with medium confidence; UniProt predicts a signal peptide or a membrane-spanning region. PROTAC: a small molecule that binds it is known.
Target class: Relaxin receptor; Relaxin-like peptide receptor (family A GPCR); Family A G protein-coupled receptor; Peptide receptor (family A GPCR); Membrane receptor
Chemical probes: RLX-33
Gene: Protein-coding gene on chromosome 5 (33,936,386 to 33,938,918, forward strand). Ensembl gene ENSG00000182631.
Subcellular location: Cell membrane
Pathways (Reactome):
Signal Transduction: G alpha (i) signalling events; Relaxin receptors
Gene Ontology:
Molecular function: G protein-coupled receptor activity; galanin receptor activity
Biological process: positive regulation of cytokinesis; G protein-coupled receptor signaling pathway; neuropeptide signaling pathway
Cellular component: plasma membrane; membrane
Genetic constraint (gnomAD): Loss-of-function variants: 31 observed, 27.21 expected, observed/expected ratio (o/e) 1.14, 90% interval 0.86 to 1.54. The upper end of that interval is the gene's LOEUF score, 1.54, which puts it in group 6 of 6, group 1 being the genes least tolerant of losing a copy. Missense variants: 684 observed, 661.35 expected, observed/expected ratio (o/e) 1.03, 90% interval 0.97 to 1.1. Synonymous variants: 351 observed, 299.25 expected, observed/expected ratio (o/e) 1.17, 90% interval 1.07 to 1.28.
Homologues: Orthologues: chimpanzee RXFP3 (99% identical), macaque RXFP3 (94% identical), pig RXFP3 (89% identical), dog RXFP3 (81% identical). Paralogues in human: GPR183 (18% identical), GPR174 (18% identical), GPR132 (17% identical), GPR151 (16% identical), P2RY11 (16% identical), GPR141 (13% identical), GPR146 (10% identical).
Diseases named in the same sentence as RXFP3 in open-access papers:
RXFP3 is named in the same sentence as 35 diseases in open-access papers, as found by Europe PMC text mining. Sharing a sentence is not in itself a finding about the gene and the disease. The quoted sentences say what the papers report.
Anxiety (16 papers, 2012 to 2023). Intense feelings of nervousness, tension, or panic often arise in response to interpersonal stresses. "Our outcomes of interest in this association study include depression, atypical depression, anxiety and metabolic syndrome, each of which has previously been linked to the relaxin-3/RXFP3 across the pertinent literature of animal studies." (PMID 37967073, 2023). "The relaxin-3/RXFP3 system has been implicated in the modulation of depressive- and anxiety-like behaviour in the animal literature; however, there is a lack of human studies investigating this signalling system." (PMID 37967073, 2023). "RXFP3 has been implicated in stress response, anxiety, depression, feeding, arousal and alcohol addiction using RXFP3/RLN3 deficient mouse models." (PMID 31794429, 2019). "Long-lasting, stress-induced adaptations to alcohol drinking behaviour have been reported in mice and relaxin-3/RXFP3 signalling is implicated in the regulation of chronic anxiety associated with prior stress exposure." (PMID 25849482, 2015). "Concordant with this, it has been shown that female RXFP3 knock-out mice present with more heightened anxiety behavior than male RXFP3 knock-out mice in assessments of anxiety, such as the elevated plus maze." (PMID 35457203, 2022). "While acute effects of RXFP3 stimulation can generate anxiolytic effects, it has recently been shown that chronic localized RXFP3 stimulation instead can actually promote anxiety behavior." (PMID 35457203, 2022). "In rodents the RLN3/RXFP3 signaling system, with RLN3 neurons originating in the NI, has been implicated in the control of food intake, stress responses (including freezing), anxiety, addiction, locomotor activity, memory, and other arousal-related behaviors." (PMID 36277494, 2022). "Previous studies have shown that the cognate ligand of RXFP3, relaxin-3, plays regulatory roles in appetite, arousal, memory, stress, anxiety and depression, thereby making this receptor an attractive target for drug discovery." (PMID 34946593, 2021). "Anatomical and pharmacological evidence suggests a role for relaxin‐3/RXFP3 signalling in motivation, anxiety and stress‐related behaviours, circadian rhythms and learning and memory." (PMID 31374129, 2019). "Overall, this suggests that RXFP3 is involved in the central processing of sensory signals and supports the possible modulatory role of the relaxin-3/RXFP3 system in stress and anxiety, feeding and metabolism and arousal and behavioural activation." (PMID 22876314, 2012). "Previous studies have suggested a role for the neuronal relaxin-3/RXFP3 system in feeding and metabolism, behavioural activation and arousal and anxiety-like behaviour and the stress response." (PMID 22876314, 2012). "Given the role identified for the relaxin-3/RXFP3 system in the MS and the generation of hippocampal theta rhythm, it was important to assess the anxiety of rats following administration of rAAV1/2 EmGFP miR499." (PMID 22876314, 2012). "The tissue distribution and function of Relaxin-3 and RXFP3 indicate potential therapeutic application of RXFP3 modulators to treat stress/anxiety, cognitive disorders and metabolic diseases." (PMID 22347403, 2012). "RLN-3/RXFP3 deficiency did not prove effective in altering anxiety, anhedonia, and social interactions in a model of cessation of exposure after chronic methamphetamine administration." (PMID 36004833, 2022). "Hence, male RXFP3 knock-out mice spent more time in the open arms of the maze indicating their lower levels of anxiety than their female RXFP3 knock-out counterparts." (PMID 35457203, 2022). "However, a later murine model testing an RXFP3 agonist demonstrated decreased cumulative neurogenic stressors and anxiety-like behavior, namely in mice with former exposure to anxiety tests." (PMID 36004833, 2022). "In addition, research by other groups has elucidated possible roles for RXFP3 in stress responses, anxiety, depression, feeding, arousal, and alcohol addiction." (PMID 35457203, 2022).
Anxiety (continued). "Moreover, RXFP3 is also postulated to modulate memory, stress, anxiety and depression, implying its potential to serve as a target for treatment of various central nervous system (CNS) diseases." (PMID 34946593, 2021). "Here, we review published experimental data on relaxin-3/RXFP3 systems in rodents, and attempt to highlight aspects that are relevant and/or potentially translatable to the etiology and treatment of major depression and anxiety." (PMID 24711793, 2014). "Thus, it appears that the anxiety-related activities of RXFP3 may be highly context specific in experimental animal models." (PMID 35457203, 2022). "Recently, therapy of anxiety, depression, and related disorders in rats was targeting the RLN-3/RXFP3 system via intranasal delivery of an RLN-3 mimetic with positive results." (PMID 36004833, 2022). "Intracerebroventricular (icv) infusions of relaxin-3 and selective RXFP3 agonists in rat activate PVN CRF neurons and the HPA axis, and modulate anxiety and depressive-like behaviour, respectively." (PMID 25849482, 2015). "There is also evidence to suggest that through common activities related to stress responses RXFP3 and GIT2 together may contribute in a coordinated manner to interconnect anxiety behaviors and stress responses such as hyperphagia or binge-eating." (PMID 35457203, 2022). "Receptor expression profiles suggest that RXFP3 is a brain neuropeptide receptor and RXFP4 a gut hormone receptor with the relaxin‐3/RXFP3 system modulating feeding [596, 597, 749, 1777, 1830], anxiety [1694, 2204], and reward and motivated goal‐directed behaviours [821, 1694, 2055]." (PMID 29055040, 2017). "Therefore, further studies are required to identify specific effects of RXFP3 (and RXFP1) activation in hypothalamus and other areas in altered feeding and metabolism and anxiety-like behavior." (PMID 24065955, 2013). "It is important to recognise that a lack of significant associations in this candidate gene study does not rule out a role for the relaxin-3/RXFP3 system in MDD, atypical depression, anxiety or metabolic syndrome." (PMID 37967073, 2023).
depression (6 papers, 2014 to 2023). "No candidate SNPs were associated with any of the three atypical depression phenotypes following corrections for multiple test burden, with rs42868 from RXFP3 closest to demonstrating any significant association (unadjusted p = 0.0297)." (PMID 37967073, 2023). "Although research in this area is still in its relative infancy, several key features have highlighted relaxin-3/RXFP3 systems as an attractive putative target for the treatment of cognitive deficits, and neuropsychiatric disorders, including depression." (PMID 24711793, 2014).
cervical cancer (4 papers, 2014 to 2024). A primary or metastatic malignant neoplasm involving the cervix. "The aim was to investigate the diagnostic value provided by methylation biomarkers of six tumor suppressor genes (ASTN1, DLX1, ITGA4, RXFP3, SOX17 and ZNF671) for cervical precancerous lesions and cervical cancer." (PMID 36803573, 2023). "The methylation positive rates of RXFP3 and ITGA4 in cervical cancer were significantly higher than those in CIN1." (PMID 36803573, 2023). "In previous studies we have shown that hypermethylation of CpG islands in proximity to the genes DLX1, ITGA4, RXFP3, SOX17, and ZNF671 correlated with the presence of cervical precancerous lesions and cervical cancer." (PMID 30509219, 2018). "A methylation signature comprising the 5′ regions of the genes DLX1, ITGA4, RXFP3, SOX17 and ZNF671 specific for CIN3 and cervical cancer (termed CIN3+) was identified and validated." (PMID 24647315, 2014). "In cervical cancer a DNA hypermethylation marker panel consisting of the six marker regions ASTN1, DLX1, ITGA4, RXFP3, SOX17, and ZNF671 may be a useful tool for triaging HPV-positive women." (PMID 30509219, 2018). "DNA isolated from 49 tissue samples with no histological evidence for CIN (normal), from 43 samples diagnosed as CIN3 and from 54 cervical cancer tissues was bisulfite-treated and used in qMSP experiments for the five marker regions DLX1, ITGA4, RXFP3, SOX17, and ZNF671." (PMID 24647315, 2014).
mental disorder (4 papers, 2014 to 2019). A disease that has its basis in the disruption of mental process. "Therefore, further studies of the neurotransmitter and neurochemical phenotype of septal and hippocampal neurons that express Rxfp3 mRNA and their precise functional roles are warranted in both normal adult rats and mice, and in models of neuropathology and cognitive and psychiatric disorders." (PMID 29403361, 2017).
Obesity (4 papers, 2014 to 2022). Accumulation of substantial excess body fat. "With respect to the links between the RLN3/RXFP3 system and human obesity it has been shown that RLN3 genetic polymorphisms are significantly associated with traits including obesity, hypercholesterolemia, and diabetes." (PMID 35457203, 2022). "The intersection of RLN3/RXFP3 signaling between stress-responsive binge eating and this greater role of RXFP3 in predisposition to obesity demonstrates the importance of this system in the control of glucometabolic dysfunction in the aging context." (PMID 35457203, 2022). "Interestingly, a polymorphism within the RXFP3 gene was significantly associated with obesity, while one polymorphism in the relaxin-3 gene and two in the RXFP3 gene were significantly associated with hypercholesterolemia." (PMID 24711793, 2014). "Determining whether RXFP3 antagonists are protective against the obesity and metabolic syndromes induced by high fat diets in rodents is also a logical and important goal." (PMID 24711793, 2014).
cognitive deficits (2 papers, 2012 to 2014). "It is possible, however, that modulation of endogenous relaxin-3/RXFP3 signaling might reduce the severity of the negative affective symptoms and cognitive deficits displayed in schizophrenic patients." (PMID 24711793, 2014).
endometrial carcinoma (2 papers, 2014 to 2021). A malignant tumor arising from the epithelium that lines the cavity of the uterine body. "Hypermethylation of the relaxin/insulin-like family peptide receptor RXFP3 promoter region was shown to be associated with microsatellite instability in endometrial carcinomas." (PMID 24647315, 2014). "When combined with the ligand, RXFP3 activates downstream kinase pathways via multiple networks, such as, protein kinase C. The RXFP3 methylation status has a strong correlation with microsatellite instability in endometrial cancer." (PMID 34610582, 2021).
schizophrenia (2 papers, 2019 to 2022). A major psychotic disorder characterized by abnormalities in the perception or expression of reality. "Relaxin ligands, as well as RXFP3 itself, have been suggested by some researchers to be implicated in schizophrenia-related conditions." (PMID 35457203, 2022). "While this connection between RXFP3 and schizophrenia has previously not yet been made, as RXFP3 plays a potential role in dopamine transmission and protection against oxidative stress, shown in this paper, this association with schizophrenia is not entirely surprising." (PMID 31794429, 2019).
aortic aneurysm (1 paper, 2019). A ruptured aneurysm located in the wall of the proximal portion of the descending aorta proceeding from the arch of the aorta. "We see only one protein overlapping with ‘aortic aneurysm’ for the RXFP3 ‘stress’ dataset, namely PHGDH (Phosphoglycerate Dehydrogenase) and none for the RXFP3 ‘control’ set." (PMID 31794429, 2019).
autism (1 paper, 2016). Persistent deficits in social interaction and communication and interaction as well as a markedly restricted repertoire of activity and interest as well as repetitive patterns of behavior. "One of the relaxin family peptide members is RXFP-3 and it is a potential drug target for autism treatment." (PMID 28000768, 2016).
cervical intraepithelial neoplasia (1 paper, 2025). "A panel of six methylation markers (ASTN1, DLX1, ITGA4, RXFP3, SOX17, ZNF671; GynTect® assay) has shown promise in diagnosing cervical intraepithelial neoplasia (CIN)." (PMID 40022051, 2025).
dysplasia (1 paper, 2025). A usually neoplastic transformation of the cell, associated with altered architectural tissue patterns. "Five of the six markers (ASTN1, ITGA4, RXFP3, SOX17, and ZNF671) showed good positivity in vulvar dysplasia but with unexpected high positivity in VLSIL (VIN I) FFPE samples compared to higher dysplasia grades." (PMID 40022051, 2025).
head and neck cancer (1 paper, 2021). A primary or metastatic malignant neoplasm affecting the head and neck. "We also show that RXFP3 and RFPL3S expression is significantly higher in head and neck cancer tissues compared with noncancer controls." (PMID 34885177, 2021).
neuroendocrine disorder (1 paper, 2013). A disease or disorder that affects the neuroendocrine gland, any of the organized aggregations of cells that function as secretory or excretory organs and that release hormones in response to neural stimuli. "Current evidence identifies RXFP3 as a potential therapeutic target for treatment of neuroendocrine disorders and related behavioral dysfunction." (PMID 24065955, 2013).
oral cancer (1 paper, 2021). "In stark contrast, decreased RXFP3 expression suggests that oral cancer cells fail to perambulate increased DNA damage, a phenomenon that is associated with heightened metabolism and ROS production and occurs in response to ARG1 overexpression." (PMID 34885177, 2021). "However, considering that ARG1 overexpression led to downregulation of RXFP3, it is tempting to speculate that this signaling axis may dampen oral cancer cellular ability to cope with DNA damage stress." (PMID 34885177, 2021).
neurological diseases (1 paper, 2013). "Relaxin-3 is involved in a wide range of behaviors, including feeding, stress responses, arousal, and cognitive processes and therefore targeting of RXFP3 may be relevant for a range of neurological diseases." (PMID 23440673, 2013). "Hence targeting of RXFP3 may be relevant for a range of neurological diseases." (PMID 23440673, 2013).
tumour (1 paper, 2014). "We then asked whether relaxin-3 exerts its effect via its specific receptor RXFP3 or via RXFP1 in both tumour cells and brain." (PMID 23963762, 2014). "In the tumour cells, we could detect only RXFP1 and 2, RXFP3 was absent (not shown for 4T1)." (PMID 23963762, 2014).
RXFP3 also shares sentences with these, for which no sentence is quoted: eating disorder (3 papers); metabolic syndrome (2); alcohol addiction (1); Alzheimer disease (1); brain diseases (1); cancer (1); cognitive disorder (1); congenital malformations (1); cutaneous melanoma (1); deafness (1); dementia (1); developmental delay (1); frontotemporal dementia (1); Hypercholesterolemia (1); metabolic disease (1); non-melanoma skin carcinoma (1); oculocutaneous albinism (1); Pigmentary retinopathy (1).